ENSG00000238575
Synonyms: LOC124904380
Gene: Small nucleolar RNA gene on chromosome 18 (2,555,358 to 2,555,492, forward strand). Ensembl gene ENSG00000238575.
Gene Ontology:
Biological process: RNA processing
Cellular component: nucleolus
Homologues: Paralogues in human: SCARNA18B (91% identical), SCARNA18 (83% identical).